PCP4 (Purkinje cell protein 4)
Description:
Functions as a modulator of calcium-binding by calmodulin. Thereby, regulates calmodulin activity and the different processes it controls. For instance, may play a role in neuronal differentiation through activation of calmodulin-dependent kinase signaling pathways.
Synonyms: PEP-19
Tractability: No criterion of Open Targets' tractability assessment is met for any kind of drug.
Gene: Protein-coding gene on chromosome 21 (39,867,438 to 39,929,397, forward strand). Ensembl gene ENSG00000183036.
Subcellular location (Human Protein Atlas): Nucleoli fibrillar center; Nucleoplasm
Gene Ontology:
Molecular function: calcium ion binding; calmodulin binding; protein binding
Biological process: positive regulation of CAMKK-AMPK signaling cascade; positive regulation of neuron differentiation
Cellular component: cytosol; nucleus; protein-containing complex; cytoplasm
Genetic constraint (gnomAD): Loss-of-function variants: 3 observed, 5.01 expected, observed/expected ratio (o/e) 0.6, 90% interval 0.27 to 1.5. That is too few expected variants to judge how well the gene tolerates losing a copy. Missense variants: 34 observed, 54.78 expected, observed/expected ratio (o/e) 0.62, 90% interval 0.47 to 0.83. Synonymous variants: 17 observed, 17.22 expected, observed/expected ratio (o/e) 0.99, 90% interval 0.67 to 1.48.
Homologues: Orthologues: chimpanzee PCP4 (100% identical), macaque PCP4 (100% identical), pig PCP4 (100% identical), guinea pig PCP4 (98% identical), mouse Pcp4 (97% identical), dog PCP4 (76% identical), rabbit PCP4 (74% identical), zebrafish PCP4 (73% identical), rat Pcp4 (69% identical), zebrafish pcp4a (68% identical). Paralogues in human: PCP4L1 (44% identical).
Diseases named in the same sentence as PCP4 in open-access papers:
PCP4 is named in the same sentence as 63 diseases in open-access papers, as found by Europe PMC text mining. Sharing a sentence is not in itself a finding about the gene and the disease. The quoted sentences say what the papers report.
breast carcinoma (11 papers, 2014 to 2024). "The Purkinje cell protein 4 (PCP4) is a calmodulin-binding anti-apoptotic peptide in neural cells and an estrogen-inducible peptide in breast cancer cell lines." (PMID 38509416, 2024). "Purkinje cell protein 4 (PCP4), also called PEP19, has been demonstrated to promote the migration, invasion and adhesion of human breast cancer MCF‐7 and T47D cells." (PMID 39233332, 2024). "PCP4 is often expressed together with Purkinje cell peptide (PEP) as a peptide in breast cancer, and they inhibit apoptosis of breast cancer cells while enhancing migration and adhesion of cancer cells." (PMID 37889013, 2023). "We previously reported PCP4/PEP19 expression in human breast cancer and found that it exerts antiapoptotic functions, cell proliferation, invasion, adhesion, and aromatase expression in human breast cancer cells." (PMID 35008217, 2021). "PCP4 is a protein that promotes the differentiation of nerve cells, and research suggested that PCP4/PEP19 can promote the migration and invasion of breast cancer." (PMID 33968130, 2021). "Our previous study demonstrated that the PCP4/PEP19 expression is induced by E2 in ER+ MCF-7 human breast cancer cells and is constitutively higher in ER- SK-BR-3 cells." (PMID 30038708, 2018). "On the other hand, some studies showed that the Purkinje cell protein 4/peptide 19 (PCP4/PEP19) is expressed in the human breast cancer tissues as an estrogen target gene." (PMID 30038708, 2018). "We also detected PCP4/PEP19 expression in human breast cancer and found that it exerts anti-apoptotic functions in human breast cancer cell lines via CaMKK and Akt signaling pathways." (PMID 27384474, 2016). "In the present study, we demonstrated that loss of PCP4/PEP19 expression decreased cell adhesion, migration, and invasion in MCF-7 and T47D human breast cancer cells." (PMID 27384474, 2016). "Taken together with our previous results demonstrating that phosphorylation of Akt is reduced by PCP4/PEP19 knockdown, our current findings implicate PCP4/PEP19 as a novel factor in the upregulation of EMT in human breast cancer." (PMID 27384474, 2016). "The specific aim of this study was to evaluate the expression and function of PCP4/PEP19 in relation to cellular proliferation of cultured human breast cancer cell lines." (PMID 25153723, 2014). "Extrapolating from the results obtained from the in vitro studies, it is probable that PCP4/PEP19 is highly expressed in human breast cancer tissues in clinical samples." (PMID 25153723, 2014). "In conclusion, our results indicate an anti-apoptotic function of PCP4/PEP19 in human breast cancer cells." (PMID 25153723, 2014). "We investigated the expression of PCP4/PEP19 in the human breast cancer cell lines, MCF-7, SK-BR-3, and MDA-MD-231, and found that it was expressed in both estrogen receptor (ER)-positive MCF-7 and ER-negative SK-BR-3 cells." (PMID 25153723, 2014). "We investigated the expression of PCP4/PEP19 in human breast cancer cell lines MCF-7, SK-BR-3, and MDA-MB-231 cells, and found that estrogen receptor (ER)-positive MCF-7 and ER-negative SK-BR-3 cells expressed PCP4/PEP19." (PMID 25153723, 2014). "The consistent overexpression of PCP4 in all CDDP-resistant TGCT cell lines may parallel observation showing that PCP4 regulates apoptosis in breast cancer cells." (PMID 33473258, 2020). "In this study, we demonstrated that the PCP4/PEP19 could induce aromatase expression in ER- SK-BR-3 human breast cancer cells." (PMID 30038708, 2018). "Since both aromatase and aldosterone synthase are one of CYP family of steroid hormone biosynthesis, we have an idea that the PCP4/PEP19 may function in the gene regulation of aromatase expression in the human breast cancer cells." (PMID 30038708, 2018). "The functions of PCP4/PEP19 would be divergent among the human breast cancer cell lines." (PMID 30038708, 2018).
breast carcinoma (continued). "Since the intratumoral estrogen-production correlates with prognosis of the breast cancer patients, additional study to clarify the relation between PCP4/PEP19 and aromatase expression would be very important to further understand the breast cancer proliferation and progression." (PMID 30038708, 2018). "PCP4/PEP19 has an anti-apoptotic function in human breast cancer cell lines." (PMID 27384474, 2016). "Given that increased motility and suppression of apoptosis promotes cancer cell survival, these results suggest that PCP4/PEP19 can potentially serve as a molecular therapeutic agent designed to suppress breast cancer cell proliferation, invasion, and metastasis." (PMID 27384474, 2016). "More specifically, we speculated that the expression of PCP4/PEP19 would be up-regulated by estrogen and mediate anti-apoptotic functions in human breast cancer cells." (PMID 25153723, 2014). "To our knowledge, we are the first to demonstrate that PCP4/PEP19 actively prevents apoptosis in human breast cancer cells, suggesting that PCP4/PEP19 can potentially serve as a novel drug target to enhance apoptotic cell death irrespective of the status of ER expression." (PMID 25153723, 2014). "Most of the tumor tissues were positive for PCP4/PEP19 irrespective of hormone receptor status, indicating that PCP4/PEP19 may present an attractive and alternative therapeutic target in breast cancer, especially in hormone-independent breast cancers." (PMID 25153723, 2014). "The Purkinje cell protein 4/peptide 19 (PCP4/PEP19) is a novel breast cancer cell expressing peptide, originally found in the neural cells as an anti-apoptotic factor, could inhibit cell apoptosis and enhance cell migration and invasion in human breast cancer cell lines." (PMID 30038708, 2018). "In addition to the PCP4/PEP19 functions inhibiting apoptosis and increasing migratory and invasive activities, the present study indicates a new function, by which PCP4/PEP19 would enhance breast cancer cell proliferation by promoting paracrine estrogen-signaling via aromatase expression." (PMID 30038708, 2018). "The PCP4/PEP19 is an estrogen-inducible peptide and expressed in the human breast cancer tissues and breast cancer cell lines." (PMID 30038708, 2018). "The PCP4/PEP19 expression enhances tumor survival by its anti-apoptotic effect and increased activities of migration and invasion in human breast cancer cell lines." (PMID 30038708, 2018). "In this study, the regulation of aromatase expression and transcription by PCP4/PEP19 was investigated in MCF-7 and SK-BR-3 human breast cancer cells using promoter specific quantitative RT-PCR and luciferase reporter assay." (PMID 30038708, 2018). "In the present study we investigated the role of PCP4/PEP19 in cell morphology, adhesion, migration, and invasion in MCF-7 and T47D human breast cancer cell lines." (PMID 27384474, 2016). "We recently demonstrated that PCP4/PEP19 is expressed and inhibit apoptosis in human breast cancer cell lines." (PMID 27384474, 2016). "In addition to anti-apoptotic, migratory and invasive activities of the PCP4/PEP19, our results indicated the PCP4/PEP19 enhances aromatase expression in ER- SK-BR-3 human breast cancer cells." (PMID 30038708, 2018). "In summary, PCP4/PEP19 upregulates aromatase gene expression mediated through PI.1 promoter transcriptional activity in ER- SK-BR-3 but not in ER+ MCF-7 human breast cancer cells." (PMID 30038708, 2018). "Although PCP4/PEP19 was first detected in the central nervous system, it is also known to be expressed in other organs, including prostate, kidney, and uterus as well as breast cancer tissue." (PMID 27384474, 2016). "The overexpression of lnc-MTAP (CDKN2B-AS1), lnc-PCP4 (DSCAM-S1), and lnc-FAM (H19) in breast cells suggests that these lncRNAs may have significant role to play in breast cancer." (PMID 30159409, 2016).
breast carcinoma (continued). "PCP4/PEP19 can therefore potentially serve as independent oncotarget for therapy of PCP4/PEP19-positive breast cancers irrespective of ER expression." (PMID 25153723, 2014). "Furthermore, PCP4/PEP19 could potentially serve as a novel molecular target, serving to enhance apoptotic cell death irrespective of the status of ER expression, offering new treatment possibilities for breast cancers." (PMID 25153723, 2014). "Therefore, the CaMKK2/AMPK signal might not be involved in the cell survival mechanisms in human breast cancer SK-BR-3 cells, even though PCP4/PEP19 knockdown reduced AMPK phosphorylation." (PMID 25153723, 2014).
Alzheimer disease (5 papers, 2014 to 2026). A progressive, neurodegenerative disease characterized by loss of function and death of nerve cells in several areas of the brain leading to loss of cognitive function such as memory and language. "PCP4 encodes a neuron-specific calmodulin-binding protein and may play a role in the pathophysiology of Huntington’s disease and Alzheimer’s disease." (PMID 36138942, 2022). "Inspection of the expression of these genes confirms the higher expression of Bc1 and Prnp and the decreased expression of Pcp4 in the hippocampus (and other regions) of the Alzheimer’s disease model brain." (PMID 41160880, 2026). "A number of genes have increased expression in the Alzheimer’s disease model, especially Bc1, Prnp, and Ttr, while Pcp4 has a reduction in activity." (PMID 41160880, 2026). "The role of PCP4 is under investigation in neurological and endocrine diseases, such as polycystic ovary syndrome and Alzheimer’s disease." (PMID 36979826, 2023). "Pcp4 modulates Ca2+/calmodulin signaling but a direct role of Pcp4 in Alzheimer’s disease has not been described." (PMID 41160880, 2026).
Down syndrome (5 papers, 2020 to 2025). "Of particular interest, overexpression of PCP4 has been shown to affect the functional development of Purkinje cells with motor skill and learning impairment in the mouse models of Down syndrome during postnatal development." (PMID 32913245, 2020). "The overexpression of HSA21 genes like DYRK1A, PDE9A, PCP4, and PCNT in Down syndrome disrupts calcium homeostasis, primarily by suppressing the calcineurin pathway." (PMID 41274866, 2025).
Huntington disease (4 papers, 2014 to 2024). Huntington disease (HD) is a rare neurodegenerative disorder of the central nervous system characterized by unwanted choreatic movements, behavioral and psychiatric disturbances and dementia. "PCP4 expression is significantly altered in a region-specific manner in AD and Huntington’s disease (HD) patient brains, potentially contributing to neurodegeneration through the disruption of calmodulin signaling." (PMID 38427613, 2024). "The target genes of rno-miR-298-5p, including PCP4 and TBP, are associated with some movement abnormality disorders such as Huntington’s disease and spinocerebellar ataxia." (PMID 36138942, 2022).
leiomyoma (3 papers, 2013 to 2023). A well-circumscribed benign smooth muscle neoplasm characterized by the presence of spindle cells with cigar-shaped nuclei, interlacing fascicles, and a whorled pattern. "Several other genes in the top 10 upregulated probesets are also overexpressed in tumours including PCP4 in leiomyomas, HOXC6 in oesophageal, breast and lung carcinomas and IL16RA2 in glioblastomas, prostate cancer and adrenocortical tumours." (PMID 24148222, 2013). "In the uterus, especially, benign leiomyoma expressed PCP4/PEP19 to a greater degree compared with non-neoplastic myometrium." (PMID 25153723, 2014).
osteoporosis (3 papers, 2022 to 2025). A condition of reduced bone mass, with decreased cortical thickness and a decrease in the number and size of the trabeculae of cancellous bone (but normal chemical composition), resulting in increased fracture incidence. "PCP4 is not only a vital protein associated with Purkinje cell development, neurite outgrowth, and calcium homeostasis but also a promoter of the cascade of OD and angiogenesis in BMSCs to alleviate osteoporosis." (PMID 36644009, 2023). "For example, circ_0019693 promotes osteogenic differentiation of bone marrow mesenchymal stem cells (BMSCs) by regulating miR-942-5p, which targets Purkinje cell protein 4 (PCP4) and bone-coupled angiogenesis, thereby inhibiting the development of osteoporosis (OP)." (PMID 40484970, 2025).
prostate carcinoma (3 papers, 2013 to 2025). A carcinoma that arises from epithelial cells of the prostate gland. "PCP4 expression in different prostate cancer cell lines was performed in both transcriptome and protein level." (PMID 40746562, 2025). "Loss or downregulation of Purkinje cell protein 4 (PCP4), is frequently observed in some prostate cancer patients, particularly those with castration-resistant prostate cancer (CRPC)." (PMID 40746562, 2025). "Consistent with our findings, PCP4 expression was decreased in CRPC group than in primary prostate cancer tissues and normal prostate tissues in datasets such as GSE6919, GSE21034 and GES35988." (PMID 40746562, 2025). "Regarding TCGA patients, TMPRSS2-ERG fusion was detected in 28.6% (140/489) of localized primary prostate cancer out of which 60% (84/140) exhibited both PCP4 deletion and TMPRSS2-ERG fusion." (PMID 40746562, 2025). "In this study, we demonstrate that PCP4 expression is significantly decreased in castration-resistant-prostate-cancer (CRPC) compared to both primary localized PCa and normal prostate tissues." (PMID 40746562, 2025).
alcohol abuse (2 papers, 2020 to 2025). The use of alcoholic beverages to excess, either on individual occasions ("binge drinking") or as a regular practice. "PCP4 levels are attenuated in post-mortem tissue of individuals diagnosed with alcohol use disorder as well as in the NAc of rats following 2-weeks of nicotine withdrawal." (PMID 40000848, 2025).
lung adenocarcinoma (2 papers, 2022). A carcinoma that arises from the lung and is characterized by the presence of malignant glandular epithelial cells. "Purkinje cell protein 4 (PCP4), an anti-apoptotic peptide that binds calmodulin, has been shown to promote the migration and invasion of human breast cells and to benefit the prognosis of lung adenocarcinoma patients." (PMID 36248799, 2022).
mucoepidermoid carcinoma (2 papers, 2021 to 2022). A carcinoma morphologically characterized the presence of cuboidal mucous cells, goblet-like mucous cells, squamoid cells, cystic changes, and a fibrotic stromal formation. "For example, in mucoepidermoid carcinoma, the discovery of PCP4/PEP19 and HER2 as novel prognostic markers is conducive to solving the problem of poor prognosis of cancer and can also be used in molecular-targeted therapies." (PMID 35359375, 2022).
adrenal adenomas (1 paper, 2023). "In adrenal adenomas, the overexpression of Pcp4 may be related to DNA methylation and may affect aldosterone secretion." (PMID 36979826, 2023).
adrenocortical carcinoma (1 paper, 2014). "Supporting this, PCP4/PEP19 overexpression has been found to increase the transcription of a CYP11B2 reporter gene in adrenocortical carcinoma cells that produce aldosterone." (PMID 25153723, 2014).
bladder tumors (1 paper, 2023). "In human or carious bladder tumors, the expression of PCP4 shows a decreasing trend, suggesting that the role of PCP4 is different in different cancers." (PMID 37889013, 2023).
cardiac arrhythmia (1 paper, 2018). Any disturbances of the normal rhythmic beating of the heart or MYOCARDIAL CONTRACTION. "Interestingly, TNF is linked to upregulation of Purkinje cell protein-4 (PCP4), a putative regulator of calmodulin and Ca2+/calmodulin-dependent kinase II (CaMKII) signaling, within the His-Purkinje network and contributor to cardiac arrhythmias." (PMID 29556499, 2018).
colorectal cancer (1 paper, 2023). A primary or metastatic malignant neoplasm that affects the colon or rectum. "But at present, there has not been a study completed on the association between PCP4 and colorectal cancer." (PMID 37889013, 2023).
ductal carcinoma (1 paper, 2018). "The ductal carcinoma cells expressed both PCP4/PEP19 and aromatase in 34 % cases (15/44 cases)." (PMID 30038708, 2018).
ductal carcinoma in situ (1 paper, 2014). "The expression of PCP4/PEP19 was significantly induced in the terminal end buds where mammary gland carcinoma develops, and the expression levels increased as cancer progressed from ductal carcinoma in situ to invasive ductal carcinoma." (PMID 25153723, 2014).
Hydrocephalus (1 paper, 2023). Hydrocephalus is an active distension of the ventricular system of the brain resulting from inadequate passage of CSF from its point of production within the cerebral ventricles to its point of absorption into the systemic circulation. "These workers were able to pinpoint a genetic locus sufficient to trigger hydrocephalus that contains genes and gene modifiers necessary for cilia function such as PCP4." (PMID 37761959, 2023).
invasive ductal carcinoma (1 paper, 2014). "Thirty cases of surgically resected invasive ductal carcinoma tissues were routinely processed by formalin-fixation and paraffin-embedding, and were used in immunohistochemistry assay to determine the expression and localization of PCP4/PEP19." (PMID 25153723, 2014).
leukemia (1 paper, 2010). A malignant (clonal) hematologic disorder, involving hematopoietic stem cells and characterized by the presence of primitive or atypical myeloid or lymphoid cells in the bone marrow and the blood. "The involvement of PCP4 in osteogenesis explains that abnormal bone marrow production leads to leukemia." (PMID 21044360, 2010). "The application on a dataset of leukemia patients identifies eQTLs in the regions of the GART, PCP4, DSCAM, and RIPK4 genes that regulate ADAMTS1, a known leukemia correlate." (PMID 21044360, 2010).
malignant salivary gland tumor (1 paper, 2021). "Here, we investigated the association with PCP4/PEP19, EGFR, and HER2 in MEC, which is the most common malignant salivary gland tumor." (PMID 35008217, 2021).